INS (insulin)
Diseases named in the same sentence as INS in open-access papers (continued):
Sharing a sentence is not in itself a finding about the gene and the disease.
diabetes (continued). "In addition, FSL has been associated with reductions in inpatient and emergency outpatient treatment due to acute diabetes-related events in large cohort studies in France, Sweden, the UK and the US, with benefits seen for patients on intensive insulin therapy as well as for those on basal insulin." (PMID 41257727, 2025). "Diabetes mellitus (DM) is a chronic metabolic disorder characterized by persistent hyperglycemia that results from impaired insulin secretion, insulin action, or both." (PMID 41463330, 2025). "As a better indicator of central obesity, WWI may induce diabetes through the following mechanisms: Firstly, altered adipose tissue metabolism: insulin-resistant factors such as free fatty acids (FFA), cortisol, and testosterone are active in abdominally obese individuals." (PMID 39996060, 2025). "Diabetes mellitus (DM) is a chronic complicated metabolic disorder characterized by hyperglycemia, which often results from defects in insulin secretion, insulin action, or both." (PMID 41227359, 2025). "Likewise, diabetes patients taking metformin perform better than those on other oral hypoglycemic drugs, as reported both in cross-sectional and longitudinal studies or on metformin + insulin." (PMID 41146261, 2025). "Consequently, therapeutic approaches that emphasize immunomodulation, such as restoring pancreatic β-cells function and re-establishing the insulin secretion system, may prove effective in preventing and reversing the progression of diabetes." (PMID 41185072, 2025). "Therefore, sphingomyelins, such as C16:0, C16:1, C18:1, and C24:1, may serve as potential prognostic biomarkers for diabetes and its complications, reflecting insulin secretion and β-cell function." (PMID 41373836, 2025). "Diabetes mellitus (DM) is a chronic metabolic disorder characterised by elevated blood glucose levels, primarily resulting from insulin resistance or impaired insulin secretion due to pancreatic dysfunction." (PMID 40844026, 2025). "Finally, T1DM, T2DM, pregnancy during intensive insulin therapy, monitoring during regular physical exercise, new onset of diabetes, and frailty have been recognized as the clinical scenarios best fitting the need for using rtCGM or isCGM, regardless of baseline HbA1c or individualized HbA1c target." (PMID 40565985, 2025). "This process contributes to maintaining optimal insulin secretion and protecting against endoplasmic reticulum stress-induced apoptosis, highlighting the essential role of mTOR in regulating energy homeostasis and preventing the progression of metabolic dysfunction in diabetes." (PMID 40137116, 2025). "Effective follow‐up care is also a crucial aspect of diabetes management; a total of 103 patients in our study were treated with insulin (with or without oral medication), but only 59.2% of them were aware of the correct timing to withhold insulin on the day of blood sampling." (PMID 41049880, 2025). "In addition, cases of insulin-deficient, autoantibody-negative diabetes in childhood and early adulthood—particularly when accompanied by neurological dysfunction or other systemic abnormalities—should also be investigated for underlying genetic causes." (PMID 41323015, 2025). "This bidirectional relationship offers a compelling therapeutic opportunity; by modulating the microbiota with targeted antioxidant interventions, it may be possible to reduce inflammation, improve insulin sensitivity, and restore metabolic homeostasis in individuals with type 2 diabetes mellitus." (PMID 40563357, 2025).
diabetes (continued). "In individuals with T1D followed for 3 years, insulin resistance preceded and was positively associated with the development of microalbuminuria; this association was independent of diabetes duration, BMI, insulin dose, systolic/diastolic blood pressure, and HbA1c." (PMID 39998445, 2025). "Additionally, DWMH exhibited stronger correlations with diabetes (47.0% vs. 34.8%, p = 0.009) and hyperuricemia (29.5% vs. 21.0%, p = 0.04) compared to PWMH (diabetes p = 0.04), likely mediated by synergistic blood–brain barrier disruption from insulin resistance and oxidative stress." (PMID 40937180, 2025). "However, further research is warranted to evaluate whether the renal benefits of SGLT2is vary according to diabetes severity, including stratification by baseline insulin use." (PMID 40429346, 2025). "Prevention of diabetes mellitus is possible by respecting hygiene and dietary rules and treatment in conventional medicine is based on the use of hypoglycemic agents such as insulin and oral antidiabetics (biguanides, sulphonamides, glinides, thiazolidinediones, etc.)." (PMID 40370420, 2025). "Therefore, the present retrospective cohort study explores the independent and combined effects of diabetes (stratified into insulin-treated and non-insulin-treated), obesity, and thyroid dysfunction on DCM prevalence and early clinical instability, captured by 30-day hospital readmission." (PMID 41153651, 2025). "In a single previously published case series, vimentin/glucagon and vimentin/insulin co-staining were seen in deceased organ donors with and without type 2 diabetes, with higher numbers of co-expressing α-cells than β-cells and higher numbers of both altered phenotypes in diabetes." (PMID 39836539, 2025). "Despite receiving insulin treatment, the minimum HbA1c value of 9.6 mg/dL indicates that not all participants are within the target range according to the reference values in the Turkish Endocrinology and Metabolism Guidelines Diabetes Mellitus Diagnosis and Treatment Guide." (PMID 41304478, 2025). "Consequently, IGF-1 may serve as an integrative biomarker of metabolic health in elderly diabetics, reflecting the collective status of insulin signalling, inflammation, and metabolic dysregulation." (PMID 41393761, 2025). "The synergistic effect of the two may be related to the regulation of the cytoskeleton during the transport and fusion of insulin secretion granules in pancreatic islet β‐cells, and abnormal insulin secretion in pancreatic islet β‐cells is closely related to the onset of diabetes." (PMID 40801824, 2025). "Diabetes Mellitus (DM) is a common endocrine metabolic disorder primarily characterized by insulin resistance, impaired insulin secretion, and abnormally elevated hepatic glycogen production." (PMID 40510484, 2025). "In the 2017–2023 period, we generated a multivariable logistic regression where glycemic control (HBA1C < 7%) was the outcome, including all predictors associated with glycemic control as p < 0.1, adjusted for diabetes treatment status (insulin, oral medication, both, or neither)." (PMID 40736548, 2025). "Moreover, the effective use of diabetes technology requires considerable knowledge and skills from both adolescents and their caregivers, who must navigate complex information that directly influences insulin therapy." (PMID 41003281, 2025). "Diabetes mellitus (DM) is a chronic disease of persistently elevated blood glucose due to abnormal beta cell production of insulin and/or insulin action." (PMID 41153701, 2025). "Type 2 diabetes mellitus (T2DM) is one of the major subtypes of DM, and its pathogenesis is more complex, involving insulin resistance and insulin secretion dysfunction." (PMID 40520185, 2025). "Diabetes mellitus (DM) is a chronic metabolic disorder marked by elevated blood glucose levels, arising either from insufficient insulin production (Type 1 DM), resistance to insulin (Type 2 DM), or both." (PMID 41050569, 2025).
diabetes (continued). "Diabetes mellitus (DM) is a chronic condition marked by high blood glucose levels due to insufficient insulin production or poor utilization." (PMID 41291962, 2025). "Additionally, longstanding diabetes and cumulative metabolic burden may contribute to hypovitaminosis D through mechanisms involving insulin resistance and β-cell dysfunction." (PMID 41439946, 2025). "Our data suggests that the patients who are not trained by a diabetes education specialist may make errors in insulin use and administration, leading to loss of glycemic control." (PMID 40376558, 2025). "In addition, starting insulin treatment is often a sign of disease progression that may further increase the fears of diabetes complications." (PMID 39972441, 2025). "Diabetes mellitus (DM) is a chronic metabolic disorder characterized by persistent hyperglycemia due to impaired insulin secretion, insulin resistance, or both." (PMID 41302460, 2025). "Moreover, insulin dosage itself is a critical factor; patients on higher insulin doses experience significantly lower remission rates, emphasizing the dose-dependent impact of insulin on diabetes remission outcomes." (PMID 40005466, 2025). "This may be type 1 or type 2 diabetes mellitus, although in reality, it is mostly a mixed picture, presenting in a state of non-insulin dependence, with likely rapid progression to requirement for insulin replacement." (PMID 39891580, 2025). "Furthermore, overweight and obesity might attribute a significant role interfering with proper utilization of insulin in the body that eventually leads to diabetes." (PMID 39883731, 2025). "Diabetes mellitus (DM) is a global health crisis affecting millions, with islet transplantation emerging as a promising treatment strategy to restore insulin production." (PMID 40051625, 2025). "Diabetes mellitus (DM), commonly referred to as diabetes, is a chronic metabolic disorder characterized by high blood glucose levels due to insufficient insulin production (type 1 diabetes) or insulin resistance (type 2 diabetes [T2D])." (PMID 41190280, 2025). "Because they do not manage their diabetes with percutaneous glucose monitoring or insulin injection, physicians or adults with diabetes may not consider them or themselves to be high-risk individuals." (PMID 41149058, 2025). "Diabetes mellitus (DM), a chronic metabolic disorder characterized by persistent hyperglycemia resulting from inadequate insulin production, resistance to insulin’s peripheral effects, or both, poses a significant health challenge globally." (PMID 39787127, 2025). "Diabetes mellitus (DM) is a metabolic illness that develops in the pancreas as it cannot create enough insulin for the body, or when it cannot utilize it effectively in some situations." (PMID 40772023, 2025). "However, since insulin resistance is one of the key pathophysiological mechanisms of T2D, insulin treatment can still contribute to this resistance, which is why it should be used at key moments in diabetes, titrating in a timely manner and addressing each situation specifically." (PMID 41012462, 2025). "A major contributor to vascular complications is diabetes mellitus (DM), which is characterised by persistent hyperglycaemia, β-cell dysfunction and insulin resistance." (PMID 40967652, 2025). "Nonetheless, CPAP therapy has been shown to reduce certain OSA-related complications, lower glucose levels in patients with DM, and improve insulin sensitivity in individuals with prediabetes." (PMID 41007822, 2025). "Insulin pump users with parents or guardians from higher socioeconomic backgrounds may experience greater collaboration with healthcare providers to promote optimal diabetes management, thus promoting use of this technology within their own communities." (PMID 40718276, 2025).
diabetes (continued). "While certain studies have highlighted the impact of weight loss on T2DM remission after metabolic surgery, factors like diabetes duration, glycemic control, or pre-surgery insulin therapy may exert a more significant influence, potentially diluting the effect of weight loss." (PMID 39715944, 2025). "Diabetes mellitus (DM) is a chronic metabolic disorder characterized by elevated blood glucose levels due to insulin imbalance or resistance." (PMID 40861221, 2025). "Diabetes mellitus (DM), which affects at least 10% of Hong Kong's population, is a metabolic disorder characterized by chronic hyperglycaemia due to defects in insulin secretion, insulin action, or both." (PMID 41395628, 2025). "Diabetes mellitus (DM) is a multifactorial metabolic disorder characterized by chronic hyperglycemia resulting from defects in insulin secretion, insulin action, or both." (PMID 40564936, 2025). "The European Association for the Study of Diabetes (EASD), in collaboration with the American Diabetes Association (ADA), advises CGM for all individuals with type 1 diabetes and for those with type 2 diabetes who are using multiple daily insulin injections or insulin pump therapy." (PMID 41413776, 2025). "Diabetes mellitus (DM) is a prevalent endocrine-metabolic disorder characterized by chronic hyperglycemia resulting from either impaired insulin secretion or insulin resistance." (PMID 41180181, 2025). "Metformin, an insulin‐sensitizing drug that is the first‐line treatment for type 2 diabetes mellitus (T2DM), may have a potential neuroprotective impact by up‐regulating the production of FGF21, which may prevent the onset of neurodegenerative diseases including MS." (PMID 40172524, 2025). "Diabetes mellitus (DM) is a chronic metabolic progressive disease characterised by hyperglycaemia resulting from defects in insulin secretion, insulin resistance or both." (PMID 40084525, 2025). "However, given the significant impact of diabetes on the islet capillary structure, it could be that the complex as a whole is affected, and this, in turn, could be a component in the alterations of insulin secretion seen as the disease progresses." (PMID 41380968, 2025). "Glucose tolerance and insulin secretion improve even before substantial changes in body weight; thus, part of the mechanism behind postsurgery diabetes remission may be independent of weight loss." (PMID 41409453, 2025). "Similarly, the extract of the Ajuva iva plant was found to significantly ameliorate alloxan-induced diabetes in rats by lowering blood glucose level; improving insulin and protein levels; and reducing blood urea nitrogen, creatinine, triglyceride, cholesterol, and lipid peroxidation." (PMID 40136680, 2025). "mHealth tools, including insulin management applications, wearable blood glucose meters, automated text messages, health diaries, and virtual health coaching, play a multifaceted role in diabetes management by enhancing insulin management, diabetes education, self-management, and prevention." (PMID 40218038, 2025). "Weight loss may not benefit all subjects with diabetes, especially those that have decreased insulin production, as more commonly seen in Asian populations." (PMID 40284198, 2025). "Consequently, PTB1B inhibitor has the potential to stimulate insulin-regulated glucose uptake, enhance insulin sensitivity, and mitigate insulin resistance, and it is regarded as a promising therapeutic agent for the treatment of diabetes." (PMID 40298635, 2025). "According to the International Diabetes Federation, DM has been defined as “a long-term condition that occurs when raised levels of blood glucose occur because the body cannot produce any or enough of the hormone insulin or cannot effectively use the insulin it produces”." (PMID 40077012, 2025).
diabetes (continued). "Moreover, improvements in modern diabetes care, such as intensive insulin regimens, glucose-sensing technology, and education programs introduced over the past two decades, may have mitigated the cumulative cerebral impact that earlier cohorts experienced." (PMID 41230083, 2025). "Diabetes mellitus (DM) is a metabolic disorder characterized by hyperglycemia resulting from defective insulin secretion or impaired insulin action." (PMID 41293422, 2025). "Diabetes mellitus (DM) is a persistent condition characterized by high levels of glucose in the blood due to irregularities in the secretion of insulin, its action, or both." (PMID 39453501, 2025). "Diabetes mellitus (DM) is a chronic metabolic disorder characterized by persistent hyperglycemia due to defects in insulin secretion, insulin action, or both." (PMID 41195338, 2025). "Diabetes mellitus (DM) is a chronic metabolic disorder characterized by persistent hyperglycemia resulting from impaired insulin secretion, insulin resistance, or a combination of both." (PMID 39810714, 2025). "However, DKA may also occur in individuals with previously diagnosed diabetes as the result of insulin omission, either inadvertent or deliberate." (PMID 39857941, 2025). "Furthermore, the role of diabetes self-management education and support, as discussed in the literature, is essential in equipping both patients and primary care physicians with the skills necessary to manage insulin therapy effectively." (PMID 40909026, 2025). "Additionally, low-frequency LFP increased at the onset of diabetes and decreased after insulin therapy in most rats significantly, while MS-CXApEn at all scale levels increased in the early diabetic rats, and MS-CXApEnlarge declined following hyperglycemia correction." (PMID 40564795, 2025). "Advances in continuous glucose monitoring, automated insulin delivery systems, and the availability of new agents such as SGLT2 inhibitors and GLP-1 receptor agonists have markedly improved glycaemic profiles and cardiovascular risk in patients with diabetes after kidney transplantation." (PMID 41536836, 2025). "Measurements were made of glucose and insulin dynamics (using frequently-sampled metabolic challenge tests), MRI-derived abdominal and liver fat content, serological biomarkers, and Olink plasma proteomics from 331 adults with new-onset T2D and 964 adults free from diabetes at enrolment." (PMID 40502600, 2025). "People with a shorter duration of diabetes and insulin treatment may hold different perspectives." (PMID 41358572, 2025). "However, despite strong evidence supporting WHO recommendations, there are significant fluctuations in the rates of breastfeeding, and multiple investigations have shown that women with diabetes, especially women with insulin-treated diabetes had the poorest outcomes concerning breastfeeding rates." (PMID 40353123, 2025). "Although these findings support the long-term benefits of aHCL therapy in subjects with T1DM, emerging evidence suggests that glycemic outcomes may be influenced by factors such as sex differences in insulin sensitivity, hormonal fluctuations, and behavioral aspects of diabetes management." (PMID 41464725, 2025). "In addition to increasing NO availability, nitrate may enhance plasma insulin levels, reduce hyperglycemia, and improve insulin resistance in diabetes, further contributing to nitrates’ anti-osteoporotic effects in diabetic bone." (PMID 40575264, 2025). "Type 2 diabetes mellitus (T2D) is a chronic metabolic condition characterized by persistent hyperglycemia, resulting from a combination of insulin resistance, primarily in muscle and adipose tissues, and insufficient insulin secretion from pancreatic beta cells." (PMID 40862756, 2025). "Given the decrease in the risk of hypoglycemia with the advances in diabetes pharmacotherapy, insulin and sulfonylurea use may no more be an important fall risk factor." (PMID 40097434, 2025).